DYNC2H1 (dynein cytoplasmic 2 heavy chain 1)
Description:
May function as a motor for intraflagellar retrograde transport. Functions in cilia biogenesis. May play a role in transport between endoplasmic reticulum and Golgi or organization of the Golgi in cells (By similarity).
Synonyms: hDHC11; DHC1B; DHC2; DNCH2; DYH1B; ATD3; SRPS2B; SRTD3
Tractability: Small molecule: a structure with a bound ligand is known. Antibody: UniProt places it where antibodies can reach, with medium confidence; its Gene Ontology location is reachable by antibodies, with medium confidence. PROTAC: ubiquitination databases record sites on it; its protein half-life has been measured.
Gene: Protein-coding gene on chromosome 11 (103,109,410 to 103,479,863, forward strand). Ensembl gene ENSG00000187240.
Subcellular location: Cytoplasm, cytoskeleton, cilium axoneme; Cell membrane; Cytoplasm
Subcellular location (Human Protein Atlas): Mid piece; Mitochondria; Cytosol; Nucleoplasm; Principal piece
Pathways (Reactome):
Organelle biogenesis and maintenance: Intraflagellar transport
Signal Transduction: Hedgehog 'off' state
Gene Ontology:
Molecular function: minus-end-directed microtubule motor activity; protein binding; cytoskeletal motor activity; dynein intermediate chain binding; dynein light intermediate chain binding; ATP binding
Biological process: Golgi organization; cilium assembly; cilium movement involved in cell motility; intraciliary retrograde transport; microtubule-based movement
Cellular component: cytoplasmic dynein complex; extracellular exosome; Golgi apparatus; microtubule; 9+2 motile cilium; axoneme; ciliary tip; cilium; cytoplasm; dynein complex; male germ cell nucleus; plasma membrane; apical part of cell; motile cilium
Genetic constraint (gnomAD): Loss-of-function variants: 322 observed, 411.02 expected, observed/expected ratio (o/e) 0.78, 90% interval 0.71 to 0.86. The upper end of that interval is the gene's LOEUF score, 0.86, which puts it in group 3 of 6, group 1 being the genes least tolerant of losing a copy. Missense variants: 4,119 observed, 4,203.3 expected, observed/expected ratio (o/e) 0.98, 90% interval 0.95 to 1. Synonymous variants: 1,464 observed, 1,409.3 expected, observed/expected ratio (o/e) 1.04, 90% interval 0.99 to 1.09.
Gene-disease validity (ClinGen):
ClinGen rates the evidence that DYNC2H1 causes each of these diseases.
asphyxiating thoracic dystrophy 3 (autosomal recessive): Definitive.
Homologues: Orthologues: chimpanzee DYNC2H1 (99% identical), macaque DYNC2H1 (99% identical), pig DYNC2H1 (95% identical), rabbit DYNC2H1 (95% identical), mouse Dync2h1 (93% identical), rat Dync2h1 (93% identical), guinea pig DYNC2H1 (92% identical), tropical clawed frog dync2h1 (77% identical), zebrafish DYNC2H1 (69% identical), Caenorhabditis elegans che-3 (41% identical), Drosophila melanogaster btv (33% identical), dog DYNC2H1 (19% identical). Paralogues in human: DYNC1H1 (29% identical), DNAH10 (24% identical), DNAH9 (24% identical), DNAH11 (24% identical), DNAH17 (23% identical), DNAH2 (23% identical), DNAH1 (22% identical), DNAH7 (22% identical), DNAH5 (22% identical), DNAH12 (22% identical), DNAH6 (22% identical), DNAH8 (22% identical), and 3 more.
Diseases named in the same sentence as DYNC2H1 in open-access papers:
DYNC2H1 is named in the same sentence as 51 diseases in open-access papers, as found by Europe PMC text mining. Sharing a sentence is not in itself a finding about the gene and the disease. The quoted sentences say what the papers report.
Jeune syndrome (13 papers, 2013 to 2025). Jeune syndrome, also called asphyxiating thoracic dystrophy, is a short-rib dysplasia characterized by a narrow thorax, short limbs and radiological skeletal abnormalities including "trident" aspect of the acetabula and metaphyseal changes. "Herein, we report a prenatally diagnosed case of ATD, also known as Jeune syndrome, due to compound heterozygous variants (p.Ile2430Thr and p.Leu4239Arg) in the DYNC2H1 gene." (PMID 35893076, 2022). "Asphyxiating thoracic dystrophy (Jeune’s syndrome) may be caused by mutations in ciliary genes such as DYNC2H1, and mutations in DYNC2H1 and in KIAA0753 were present in patients with recurrent respiratory infections." (PMID 38674609, 2024). "Moreover, in the recent ACMG carrier screening guidelines some genes (i.e. DYNC2H1) are listed with much higher carrier frequencies (1/50) than expected based on prevalence of the associated disorder (short-rib-polydactyly/Jeune syndrome, prevalence ~1/100’000)." (PMID 36550190, 2023). "Further, mutations in additional IFT components including TTC21B/IFT139, DYNC2H1 and WDR19/IFT144 have been reported in association with Jeune syndrome." (PMID 24009529, 2013). "Similarly, Sensenbrenner and Jeune syndromes appear to be milder presentations of the embryonically lethal short rib polydactyly syndrome as IFT80, WDR35 and DYNC2H1 are mutated in both milder and more severe phenotypes." (PMID 22829176, 2013). "Mutations in DYNC2H1 are causative mutations for short-rib thoracic dysplasia 3 with or without polydactyly (SRTD3; OMIM: 613091, also called Jeune syndrome)." (PMID 39881416, 2025). "The genotypes of DYNC2H1, IFT172 and WDR19 and the phenotypes of the fetuses give hints for the diagnosis of short-rib thoracic dysplasia (SRTD) with or without polydactyly 3, 10, and 5, respectively." (PMID 38062428, 2023).
ciliopathies (8 papers, 2016 to 2025). "The DYNC2H1 gene encodes a dynein motor protein essential for retrograde ciliary transport and is linked to ciliopathies such as short rib-polydactyly syndrome, which involves renal abnormalities." (PMID 40770708, 2025). "Multiple ciliopathies caused by mutations in DYNC2H1, WDR60, WDR34, DYNC2LI1 and TCTEX1D2 have been reported." (PMID 36632779, 2023). "The present study reports four prenatal cases of SRPS/SRTD as implicated by ultrasound findings, which provide useful information regarding the novel variants of ciliopathies-associated genes DYNC2H1, IFT172, and WDR19." (PMID 38062428, 2023). "Collectively, our case series provide information regarding the novel variants of ciliopathies-associated genes DYNC2H1, IFT172, and WDR19, and emphasize the importance of both clinical and genetic findings in the setting of prenatal diagnosis for skeletal disorders." (PMID 38062428, 2023). "Moreover, variants in DYNC2H1 were also described in types I-III short-rib polydactyly syndrome (SRPS) (Saldino–Noonan syndrome, Majewski syndrome, and Verma–Naumoff syndrome), which belong to the group of “ciliopathies with major skeletal involvement”, according to current nosology." (PMID 35893076, 2022).
pancreatic cancer (5 papers, 2017 to 2021). "At the same time, several lncRNAs (e.g., linc-ROR, GAS5 and linc-DYNC2H1-4) have been identified as ceRNAs to confer drug resistance in pancreatic cancer." (PMID 31514732, 2019). "In the present study, we found that the long intergenic non-coding RNA linc-DYNC2H1-4 was upregulated in pancreatic cancer cell line BxPC-3-Gem with acquired gemcitabine resistance." (PMID 28703793, 2017). "Collectively, our results demonstrate that miR-145 targets MMP3, as well as Oct4, Lin28, Nanog, Sox2 and ZEB1 which are upregulated by linc-DYNC2H1-4 in pancreatic cancer cells." (PMID 28703793, 2017). "Previous research has shown that Linc-DYNC2H1-4 promotes EMT and CSC phenotypes by acting as a sponge of miR-145 in pancreatic cancer cells." (PMID 33937054, 2021). "Linc-DYNC2H1–4 promotes EMT and CSC phenotypes by acting as a sponge of miR-145 in pancreatic cancer cells." (PMID 34130645, 2021). "Recent studies have demonstrated that certain lncRNAs can act as competing endogenous RNA (ceRNAs) or miRNA “sponges” to modulate chemotherapy sensitivity in pancreatic cancer, such as linc-ROR, GAS5 and linc-DYNC2H1-4." (PMID 31514732, 2019). "In summary, our results demonstrate that linc-DYNC2H1-4 is involved in the regulation of both EMT and stemness in pancreatic cancer cells." (PMID 28703793, 2017). "This study identified the linc-DYNC2H1-4 as a driver of EMT and CSC formation in pancreatic cancer cells." (PMID 28703793, 2017). "Our data strongly suggest that linc-DYNC2H1-4 acts as a sponge of miR-145 to upregulate the expression of its targets, MMP3, Oct4, Lin28, Nanog, Sox2 and ZEB1, thereby promoting EMT progression and CSC formation in pancreatic cancer cells." (PMID 28703793, 2017).
short rib-polydactyly syndrome (5 papers, 2014 to 2025). Short rib-polydactyly syndromes are a group of bone malformations characterized by a narrow thorax and polydactyly (usually preaxial). "Similarly, DYNC2H1 causes longer cilia (~4.7–5.0 μm in ATD patients) but shorter cilia in severe Short-rib-polydactyly syndrome (SRPS; ~2.3 μm)." (PMID 40615527, 2025). "Interestingly, however, members of a consanguineous family with short-rib polydactyly syndrome were found to have mutations in the dynein heavy chain DYNC2H1 resulting in decreased mRNA expression, and cultured chondrocytes from these individuals demonstrated short cilia and cells with absent cilia." (PMID 24465567, 2014).
breast carcinoma (4 papers, 2014 to 2025). "Decreased expression of DYNC2H1 as well as the other ciliary-related genes may turn off ciliogenesis and explain the loss of cilia seen in breast cancers." (PMID 24987519, 2014). "Among the 69 ciliary-associated genes analyzed, seven genes showed a statistically significant decrease in expression in breast cancers (log fold change: DYNC2H1 = -0.66; IFT46 = -1.07; PKD2 = -1.67; NPHP3 = -1.10; BBS2 = -1.51; BBS4 = -0.78; TTC8 = -1.46)." (PMID 24987519, 2014). "We further validated downregulation of DYNC2H1 protein expression in breast cancers." (PMID 24987519, 2014). "To determine if protein expression of the cilia-related gene DYNC2H1 is decreased in breast cancers we performed immunofluorescent staining of three specimens taken from normal breast reduction mammoplasties (RM) as well as five patients with invasive breast carcinoma." (PMID 24987519, 2014).
osteogenesis imperfecta (2 papers, 2023). Osteogenesis imperfecta (OI) comprises a heterogeneous group of genetic disorders characterized by increased bone fragility, low bone mass, and susceptibility to bone fractures with variable severity. "In the case 2, 5 and 8, we found the WNT1or COL1A1-related VUS in osteogenesis imperfecta, and DYNC2H1 and NEK1-related asphyxiative hypoplasia of thorax." (PMID 37875969, 2023).
cataract (1 paper, 2022). Partial or complete opacity of the crystalline lens of one or both eyes that decreases visual acuity and eventually results in blindness. "Particularly, mutations in three of them, AGBL4, DYNC2H1, and KIZ, cause retinal pathologies in humans, while a NID1 mutation was found to be the cause of the development of recessive cataracts in Romagnola cattle." (PMID 36669004, 2022).
colorectal cancer (1 paper, 2024). A primary or metastatic malignant neoplasm that affects the colon or rectum. "FBXO32, KLHL21, and DYNC2H1 were significantly downregulated and WDR34 was significantly upregulated in colorectal cancer patients." (PMID 39132155, 2024).
heart malformations (1 paper, 2023). "The c.10219C>T (p.Arg3407Ter) mutation of DYNC2H1 may be associated with severe short limbs and heart malformations in SRTD3." (PMID 37007936, 2023).
Insulin resistance (1 paper, 2024). Increased resistance towards insulin, that is, diminished effectiveness of insulin in reducing blood glucose levels. "Our trans-ethnic GWAS meta-analysis identified one additional novel susceptibility locus tagged by a SNP located in DYNC2H1, which is also associated with expression in tissues relevant to insulin resistance." (PMID 38685053, 2024).
Leber congenital amaurosis (1 paper, 2023). Leber congenital amaurosis (LCA) is a retinal dystrophy defined by blindness and responses to electrophysiological stimulation (Ganzfeld electroretinogram (ERG)) below threshold, associated with severe visual impairment within the first year of life. "DYNC2H1 is a dynein protein that is involved in retrograde transport in cilia, and its variants have been known to cause Leber congenital amaurosis." (PMID 37628652, 2023).
liver cancer (1 paper, 2023). An epithelial or non-epithelial malignant neoplasm that arises from the liver. "Moreover, the liver cancer-related driver genes RPS6KA3 and DYNC2H1 and the tumor migration-related gene CDH9 were also significantly different between the two groups." (PMID 37409259, 2023).
melanoma (1 paper, 2025). A malignant, usually aggressive tumor composed of atypical, neoplastic melanocytes.
Moyamoya disease (1 paper, 2023). Moyamoya disease (MMD) is a rare intracranial arteriopathy involving progressive stenosis of the cerebral vasculature located at the base of the brain causing transient ischemic attacks or strokes. "Using exome sequencing, the presence of multifocal FMD was associated to myosin light chain kinase (MYLK – also involved in thoracic aneurysms), dynein cytoplasmic heavy chain 1 (DYNC2H1), sarcomeric protein obscuring (OBSCN), and RNF213 (involved in Moyamoya disease) genes." (PMID 37214559, 2023).
osteoporosis (1 paper, 2026). A condition of reduced bone mass, with decreased cortical thickness and a decrease in the number and size of the trabeculae of cancellous bone (but normal chemical composition), resulting in increased fracture incidence. "Furthermore, conservation scores supported the potential pathogenicity of DYNC2H1 and NQO1, reinforcing the likelihood of their involvement in osteoporosis risk." (PMID 41515648, 2026).
polycystic kidneys (1 paper, 2023). "Variants in DYNC2H1 have been associated with a heterogeneous spectrum of conditions related to altered primary cilium function that often involve polydactyly, abnormal skeletogenesis, and polycystic kidneys." (PMID 37091781, 2023).
Polyhydramnios (1 paper, 2023). The presence of excess amniotic fluid in the uterus during pregnancy. "In our study, WES also identified a compound heterozygous variation c.8617A>G (p.Met2873Val) and c.7053_7054del (p.Cys2351Ter) of DYNC2H1 gene in fetus 2, which also presented with polyhydramnios." (PMID 37007936, 2023).
Salmonella Infections (1 paper, 2022). Infections with bacteria of the genus SALMONELLA. "For the G2 group, the main pathways were: Salmonella infection (NFKB1, TJP1, DYNC2H1), transcriptional misregulation in cancer (MET, MLLT1, NFKB1), and adherens junction (MET, TJP1)." (PMID 36012418, 2022).
Situs inversus totalis (1 paper, 2022). "This study identified a foetus with SRTD3 with situs inversus totalis with mirror-image dextrocardia in a Chinese family, revealing two novel compound heterozygous dynein cytoplasmic 2 heavy chain 1 (DYNC2H1) variants, expanding the phenotypic spectrum of SRTD3." (PMID 35277174, 2022).
skeletal dysplasia (6 papers, 2022 to 2025). Any Mendelian diseases that affects growth and development of the skeleton. "Mutations in DYNC2H1 will cause the dysfunction of primary cilia, causing a heterogeneous spectrum of conditions such as skeletal dysplasia." (PMID 37007936, 2023). "Mutations in DYNC2H1 will lead to the dysfunction of primary cilia, causing a heterogeneous spectrum of conditions such as skeletal dysplasias." (PMID 35277174, 2022). "In the current study, by using trio-WES and proband-WES study with comprehensive analysis, eight mutations (4 pairs of compound heterozygous sites) of DYNC2H1 were identified in four Chinese families with fetal skeletal dysplasia, supporting a diagnosis of SRTD3 (OMIM; 613091)." (PMID 37007936, 2023). "Our findings expand the mutation spectrum of DYNC2H1 in this rare disease and highlight the value of WES in the diagnosis of skeletal dysplasia with unclear prenatal indications." (PMID 39881416, 2025).
infection (1 paper, 2014). The state of being infected such as from the introduction of a foreign agent such as serum, vaccine, antigenic substance or organism. "While downregulation of MYO6, involved in actin-based motility, did not influence MHV infection (dark orange), our results indicate that the microtubule-associated motility proteins DYNC1H1 and DYNC2H1 are important for infection with MHV (orange)." (PMID 25375324, 2014).
retinopathies (1 paper, 2024). "While less direct evidence for involvement in EAE/MS pathogenesis exists for Dync2h1/DYNC2H1, this gene has been implicated in neurodevelopment, maintenance, neuronal transport, and retinopathies, suggesting a potential involvement in neurodegeneration." (PMID 39325545, 2024).
DYNC2H1 also shares sentences with these, for which no sentence is quoted: cancer (5 papers); asphyxiating thoracic dystrophy 3 (3); glioblastoma (3); polydactyly (3); tumor (3); Bardet-Biedl syndrome (2); genetic disease (2); glioma (2); Majewski syndrome (2); nephronophthisis 15 (2); situs inversus (2); achondroplasia (1); Arrhythmogenic right ventricular dysplasia (1); arthrogryposis (1); campomelic dysplasia (1); cardiomyopathy (1); Duane-radial ray syndrome (1); hereditary colorectal cancer (1); hypothalamic hamartoma (1); invasive breast carcinoma (1); Joubert syndrome (1); kidney disease (1); nephronophthisis (1); omphalocele (1); osteogenesis imperfecta type 1 (1); respiratory infections (1); retinal disease (1); short-rib (1); skeletal diseases (1).